BDNF (brain derived neurotrophic factor)
Diseases named in the same sentence as BDNF in open-access papers (continued):
Sharing a sentence is not in itself a finding about the gene and the disease.
Stroke (continued). "Clinical studies indicate the role of BDNF as a risk factor for stroke and a marker of the prognosis, mortality, and functional outcome in stroke survivors." (PMID 33343231, 2020). "In closing, to our knowledge this is the first study to analyze the effects of the BDNF Val66Met polymorphism in early-onset stroke patients." (PMID 33306691, 2020). "Unfortunately, during the acute phase of stroke (first day after stroke), the concentration of BDNF decreases and this is associated with low functional neurological status." (PMID 32617098, 2020). "Some studies on subacute patients after spontaneous recovery have shown a significant association between BDNF rs6265 SNP and stroke outcome." (PMID 33182716, 2020). "How BDNF elevation is linked to p38α inhibition by neflamapimod in this experimental stroke model will need to be determined in a follow-up mechanistic study." (PMID 33275615, 2020). "BDNF can interact with inflammation as the risk factor in the cardiovascular disorders, including stroke." (PMID 33343231, 2020). "Low-frequency rTMS also accelerates the motor function recovery in the affected limb after stroke by influencing BDNF gene polymorphism." (PMID 32116552, 2019). "On contrary, decreased serum BDNF was found to be associated with increased risk of incident stroke/TIA." (PMID 30767081, 2019). "In an animal study, the protecting effect of the AT1R blocker candesartan after stroke was mediated by endothelial nitric oxide (NO) synthase and it was positively associated with BDNF expression." (PMID 30767081, 2019). "A recent animal study reported enhanced overexpression of BDNF to be associated with nociceptive activity in the medial thalamus, considered a key factor in central post-stroke pain." (PMID 31632254, 2019). "While GABAergic activity has been shown to be an important contributor to plasticity after stroke, other mechanisms, such as brain derived neurotrophic factor (BDNF) and neuromodulin signaling, have been implicated as well." (PMID 31191265, 2019). "The agonist-induced redistribution of Sig-1R is linked to an increased intracellular trafficking of BDNF required for brain repair in rat models of stroke and in 6-hydroxydopamine lesion mouse model of Parkinson’s disease." (PMID 30231518, 2018). "A significant decrease in serum BDNF concentrations at the early stage of stroke predisposes to the development of PSD." (PMID 30061860, 2018). "BDNF is implicated in processes following stroke, including synaptic remodeling, which can occur for several weeks following injury." (PMID 30486515, 2018). "One study demonstrated a negative correlation between the European cardiovascular risk score and serum BDNF levels in stroke patients." (PMID 29409455, 2018). "Actually, vascular endothelial growth factor (VEGF) has been recently associated with BDNF as a biomarker in stroke, though with some criticism." (PMID 28373915, 2017). "It is believed that this beneficial effect is mediated via increased expression of growth factors, such as brain derived neurotrophic factor, which is associated with functional recovery after stroke." (PMID 29123485, 2017). "It is worth mentioning that, compared to native BDNF, a nanoparticle formulation of BDNF significantly decreases the loss of brain tissue in mice when administered up to 6 h after stroke onset." (PMID 28134845, 2017). "On the contrary, decreased serum BDNF was found to be associated with increased risk of incident stroke/TIA." (PMID 27478486, 2016). "This negative correlation is indeed in line with a recent study showing that serum BDNF levels were inversely associated with cardiovascular disease and mortality and with risk of incident stroke or transient ischemia attack." (PMID 26469350, 2015). "A higher methylation level in the promoter of the brain derived neurotrophic factor (BDNF) was reported to be associated with a poor outcome one year after stroke." (PMID 26422690, 2015).
Stroke (continued). "One of the well recognized actions of BDNF in the CNS is its neuroprotective role against the various neuronal injuries caused in neurodegenerative diseases or stroke." (PMID 24804781, 2014). "Stroke induces the loss of motor function, and rehabilitation is the process of relearning; thus, higher BDNF concentration in the brain implies learning and neural rehabilitation." (PMID 25045713, 2014). "BDNF genotype frequency distribution and association with stroke severity during the acute phase, as measured by the NIHSS." (PMID 25470006, 2014). "BDNF variants were next compared in good (mRS 0–1) versus bad (mRS 2–6) functional outcome groups after 3 months post-stroke." (PMID 25470006, 2014). "Recently, several clinical studies have analyzed rs6265 and other BDNF polymorphisms in relation to functional outcome after stroke." (PMID 25470006, 2014). "The most well studied polymorphism in BDNF, rs6265 (Val66Met), is associated with impaired activity-dependent secretion of BDNF in neurons and has been analyzed with respect to stroke severity in several clinical studies with discrepant results." (PMID 25470006, 2014). "Putting together, we found that exercise post-stroke enhanced endogenous neuroprotective effects, which should be associated with regulation of BDNF, VEGF and Nogo-A expression in the ischemic injured brains." (PMID 24260348, 2013). "In this regard, a meta-analysis indicated that lower serum BDNF levels (measured within a mean of 2 months after stroke) were associated with the presence of post-stroke depression." (PMID 23675319, 2013). "Post-stroke treatment with amphetamine facilitates behavioral recovery, which is associated with an increase in synaptogenesis and upregulation of BDNF in the lesioned cortex." (PMID 24236179, 2013). "Associations of BDNF genotype and methylation status on stroke outcomes and assessment scale scores were investigated using logistic regression, repeated measures ANOVA and partial correlation tests." (PMID 23240009, 2012). "Multivariate analyses examining the interactive effects of BDNF val66met polymorphism and promoter methylation on poor stroke outcomes at 2 weeks and at 1 year." (PMID 23240009, 2012). "It is noteworthy that measures of higher BDNF methylation status were more strongly associated with longterm stroke outcomes, while the BDNF met allele was associated with both acute and longterm outcomes." (PMID 23240009, 2012). "Using data from a longitudinal study of a post-stroke cohort, we examined the roles of BDNF val66met polymorphism and promoter methylation status on outcomes at two weeks and one year after the index stroke." (PMID 23240009, 2012). "Principal findings in this longitudinal study of a post-stroke cohort were that the BDNF val66met polymorphism was independently associated with acute and long-term poor outcomes, and with worsening of physical disability and cognitive function." (PMID 23240009, 2012). "Physical exercise constitutes an innovative strategy to treat deficits associated with stroke through the promotion of BDNF-dependent neuroplasticity." (PMID 22962604, 2012). "Our study has several strengths, as well as being the first to report on associations between BDNF methylation status and stroke outcomes." (PMID 23240009, 2012). "On the other hand, in the cortical “penumbra” region the reduced levels of total iron and BDNF in the CpKO mouse render the neurons more susceptible to death after the ischemic insult exacerbating the stroke outcome." (PMID 21949858, 2011). "Unassessed variables, such as stroke etiology and genetic polymorphisms (e.g., BDNF Val66Met), may contribute to distinct physiological profiles that influence neuroplasticity and response to exercise." (PMID 40283415, 2025).
Stroke (continued). "Along with BDNF’s role in perpetuating disease phenotypes, the prospect of BDNF in promoting neural repair and plasticity also has potential therapeutic relevance in the case of disorders associated with stroke and spinal cord injury and related rehabilitative efforts." (PMID 40362507, 2025). "Microglia contribute to synapse loss through phagocytosis or BDNF signaling after stroke." (PMID 38584255, 2024). "Interestingly, a recent study has demonstrated the promotion of axonal remodeling and restoration of abnormal synaptic structures using adeno-associated virus (AAV) vectors carrying genes encoding BDNF or TrkB in the stroke model." (PMID 38338875, 2024). "Furthermore, BDNF has been linked to improved sensorimotor recovery and functional outcomes after stroke." (PMID 38707431, 2024). "Besides, a reduced serum BDNF level has been found to enhance the PSD risk in the acute phase of stroke." (PMID 38421829, 2024). "Children with HbSS or HbSC under physiological stress may have high BDNF levels, suggesting a potential risk of stroke or pain crises." (PMID 39749215, 2024). "Moreover, the results of meta-analysis studies have shown that BDNF concentrations in patient sera significantly decrease during the early period of stroke and can predispose the patients to PSD." (PMID 38421829, 2024). "Moreover, these low BDNF levels are associated with a higher risk of stroke and transient ischemic attack and low recovery rates." (PMID 38610750, 2024). "This suggests that lipid profiles are notably associated with BDNF levels in stroke patients and implies that BDNF and lipid profiles might play a role in the pathophysiology of stroke and might be potential markers of its severity." (PMID 38397057, 2024). "In fact, several studies have shown a direct association between altered BDNF levels and stroke." (PMID 38137853, 2023). "It was also found that cognitive functions in stroke patients are impaired with an increase in the content of β-amyloid peptide and a decrease in BDNF, the mechanism of which is associated with a decrease in cyclic adenosine monophosphate and phosphorylated-cAMP-response element binding protein." (PMID 36969561, 2023). "Moreover, a clinical trial showed that lower BDNF levels are associated with increased risk of stroke/transient ischemic attack." (PMID 37950725, 2023). "In stroke patients, BDNF release has been reported as a positive prognostic factor for patients poststroke recovery so that increasing BDNF levels are associated with faster and stronger recovery, while low levels of BDNF are associated with high stroke risk and poor recovery." (PMID 38137853, 2023). "Given the known role of BDNF in brain plasticity and the theorized importance of modifying synaptic connections in the rTMS-aided recovery process from stroke, it is reasonable that a loss-of-function mutation in this gene would be associated with a smaller response to the treatment." (PMID 36188894, 2022). "We revealed that kaempferol regulates post-stroke apoptosis and neuroinflammation involved by neutrophils, and the underlying mechanism may be related to the regulation of BDNF-TrkB-PI3K/AKT signaling and JAK1/STAT3 signaling, respectively." (PMID 36293548, 2022). "And low BDNF concentration has been associated with the rising risk of stroke." (PMID 35770087, 2022). "In people with stroke, presence of the BDNF val66met polymorphism is associated with decreased brain activation in the primary sensorimotor cortex contralateral to the movement as well as slower or reduced behavioral recovery from stroke." (PMID 36556107, 2022). "As malnutrition is associated with a lower level of circulating BDNF, premorbid malnutrition may hinder the process of cognitive recovery after a stroke." (PMID 34070955, 2021). "There is a significant loss of BDNF levels in the ipsilateral striatum with stroke." (PMID 32378029, 2021).
Stroke (continued). "However, the number of clinical research studies of the role of BDNF polymorphisms in stroke is limited, and the exact influence of BDNF polymorphisms underpinning the aspects of stroke severity, recovery, and functional outcome is still unclear." (PMID 34367374, 2021). "Finally, while BDNF was associated with improved swallowing outcome in stroke patients in a previous study, DRD1 was shown to be involved with poor outcome in this study, raising the question which SNP is the critical biomarker." (PMID 34276537, 2021). "We hypothesized that the presence of the BDNF Val66Met polymorphism would affect the language function outcome after stroke." (PMID 34367374, 2021). "The correction by age and time since the stroke onset confirmed that BDNF rs6265 polymorphism significantly predicts outcome, with the probability being 5.59 times higher of obtaining a favorable outcome in patients carrying the A− allele compared to those carrying the A+ allele." (PMID 33182716, 2020). "The possibility that the BDNF Val66Met polymorphism may have a sexually dimorphic effect on stroke recovery is thus an important consideration in study design." (PMID 33306691, 2020). "BDNF exerts neuroprotective activities, which might protect against direct tissue loss resulting from ischemia in the acute phase of stroke and enable the later recovery of cell function." (PMID 32916851, 2020). "Furthermore, patients with stroke with the BDNF Val66Met polymorphism showed decreased brain activation of the ipsilesional primary sensorimotor cortex during affected hand movement compared with those without the BDNF polymorphism." (PMID 33029116, 2020). "Here, we investigated whether BDNF rs6265 polymorphism and the methylation status of the CpG site into this SNP are involved in post-stroke recovery after rehabilitation treatment." (PMID 33182716, 2020). "Some authors proposed that tDCS-induced improvement of stroke/TBI symptoms might be due to increase of BDNF expression and associated with choline/creatine ratios in the perilesional cortex." (PMID 32211039, 2020). "Additionally, a dual-luciferase reporter assay identified BDNF as the direct target of miR-210, which is a crucial ischaemic stroke-associated miRNA and a potential target for stroke therapy." (PMID 33029119, 2020). "Lower levels of BDNF are correlated with an increased risk of stroke and a poorer prognosis, and hence, the premorbid BDNF levels in the patients may have been (somewhat) lower than the levels in the healthy controls." (PMID 32916851, 2020). "Moreover, alteration in BDNF signaling can result in synaptic dysfunction that is associated with memory deficits observed in AD, Parkinson’s disease (PD), stroke, and sepsis-associated encephalopathy." (PMID 31948437, 2020). "The BDNF can also be used as a diagnostic marker of the threatening post-stroke complications." (PMID 31701356, 2020). "Potential association between the pathogenetic background of strokes and BDNF level may be of importance as this was suggested by other authors." (PMID 33343231, 2020). "Besides, the carriers of Val66Met polymorphism of BDNF, a disadvantaged variant in the function of BDNF, were worse in the locomotor adaptation after stroke." (PMID 32932791, 2020). "Moreover, we found a significant increase in the methylation levels of BDNF rs6265 SNP in patients with stroke carrying the A− allele after rehabilitation treatment." (PMID 33182716, 2020). "Finally, we compared the mean methylation percentages of the BDNF rs6265 polymorphism (A+ vs. A− alleles) in patients with stroke evaluated at T0 and T1 (n = 36)." (PMID 33182716, 2020). "Moreover, homozygous Met/Met mice showed a greater impairment of post-stroke locomotor functions and reduced angiogenesis, even if the association of BDNF rs6265 polymorphism with stroke outcomes and recovery remained inconclusive." (PMID 33182716, 2020).
Stroke (continued). "In contrast, in Met allele carriers, the activity-dependent BDNF protein in the contralesional hemisphere may remain at a similar level after stroke." (PMID 33029116, 2020). "Indeed, stroke-induced changes in BDNF protein have also been observed, with microsphere embolism-induced MCAo causing elevated BDNF expression over a similar time course." (PMID 31427916, 2019). "Moreover, our data is supported by previous work investigating the role of the BDNF Val66Met genetic polymorphism in stroke and spinal cord injury." (PMID 31787925, 2019). "BDNF has repeatedly been implicated as a growth-promoter in in vitro assays and in models of stroke; BDNF effects can further be promoted by rehabilitation training." (PMID 30962276, 2019). "The molecular mechanism underlying this axonal remodeling may rely on mature BDNF production induced by TST combined with inhibition of DNA methylation after stroke." (PMID 29997355, 2018). "Currently, it is unknown whether WBV leads to increases in hippocampal BDNF and whether this response promotes neurogenesis associated with improved cognitive outcome after stroke, but we suspect that this may be the missing link between WBV and exercise." (PMID 30217051, 2018). "Additionally, low levels of BDNF are associated with increased risk of stroke, worsening of functional outcome, and increased stroke-related mortality." (PMID 29899693, 2018). "In addition, a recent meta-analysis showed that the decrease in serum BDNF concentrations in early stroke predisposed patients to the development of PSD." (PMID 30322026, 2018). "Research suggests that polymorphisms in genes such as BDNF and apolipoprotein E may influence stroke recovery, and specifically may interact with treatments." (PMID 30034335, 2018). "Recently, single nucleotide polymorphisms of the BDNF gene were studied in patients with stroke." (PMID 29899693, 2018). "In addition, low levels of serum BDNF concentrations at the acute phase were associated with poor functional outcome at two years after stroke." (PMID 30322026, 2018). "Other conditions in which a reduction in BDNF levels was observed in the past include sleep apnea, birth stress associated with psychiatric disease later in life, and stroke with low functional outcome." (PMID 30327610, 2018). "In addition, concentrations of BDNF are reduced in the acute phase of ischemic strokes, and it is associated with the risk of stroke onset." (PMID 28865453, 2017). "The BDNF-66Met allele may be detrimental to recovery following stroke, but the evidence to date remains contentious." (PMID 27242654, 2016). "An interaction between BDNF genotype and baseline motor function may help explain the lack of consensus in the literature regarding the role of the Val66Met polymorphism in stroke recovery." (PMID 27242654, 2016). "The Framingham study examined the correlation of VEGF and BDNF serum levels with risk of stroke." (PMID 25942688, 2015). "The objective of the present study is therefore to investigate whether genetic variation at the BDNF locus is associated with stroke severity, recovery, and short-term (3-month) and long-term (2- and 7-year) functional outcome after ischemic stroke." (PMID 25470006, 2014). "At current, it is unclear whether polymorphisms in BDNF play a role in stroke severity, recovery and functional outcome after stroke." (PMID 25470006, 2014). "Literature summary of BDNF gene variants and functional outcome after stroke." (PMID 25470006, 2014). "The aims of the present study are therefore to investigate whether genetic variation at the BDNF locus is associated with initial stroke severity, recovery and/or short-term and long-term functional outcome after ischemic stroke." (PMID 25470006, 2014). "Altered BDNF plasma levels or association of BDNF genotypes indicate that this growth factor may be involved in the physiological response to stroke in humans." (PMID 23356671, 2013).